ROBO1 (roundabout guidance receptor 1)
Diseases named in the same sentence as ROBO1 in open-access papers (continued):
Sharing a sentence is not in itself a finding about the gene and the disease.
liver fibrosis (10 papers, 2018 to 2024). "Compared with the uninfected group, the schistosome-infected mice showed lower miR-29a-3p and higher Robo1 expression in liver tissues, and these expression levels were associated with the advanced stage of liver fibrosis." (PMID 37280619, 2023). "It is easy to speculate a direct association among Ccn2/Ctgf, integrins, Slit2, and Robo1 as a whole complex on HSC cell surface during liver fibrosis." (PMID 36469291, 2023). "In cardiac and hepatic fibrosis, Slit2/Robo1 signaling significantly upregulates TGF-β1 expression and activates the downstream expression of SMAD2/3." (PMID 39768930, 2024). "The present study showed that stimulation of LX-2 cells with TGF-β1, which is a typical profibrotic gene in the progression of hepatic fibrosis, downregulated the mRNA expression of miR-29a-3p and upregulated the level of Robo1 mRNA." (PMID 37280619, 2023). "The functional contributions of miR-29a-3p-Robo1 signaling in liver fibrosis and HSC activation were investigated using primary mouse HSCs and the human HSC cell line LX-2." (PMID 37280619, 2023). "Our results provide experimental and clinical evidence that the miR-29a-3p-Robo1 signaling pathway in HSCs plays an important role in the development of hepatic fibrosis." (PMID 37280619, 2023). "Robo1 is related to several types of cancer and chronic diseases, including kidney disease and liver fibrosis." (PMID 37280619, 2023). "Our data showed that miR-29a-3p was downregulated in HSCs during hepatic fibrosis, and Robo1 was upregulated." (PMID 37280619, 2023). "Immunofluorescence staining was used to detect the expression of Robo1 and the presence of HSCs, which are the main effector cells in various types of hepatic fibrosis and play an important role in linking hepatic inflammation to fibrogenesis." (PMID 37280619, 2023). "Our results showed that the expression level of Robo1 was significantly higher in liver tissues with hepatic fibrosis." (PMID 37280619, 2023). "To evaluate the effects of miR-29a-3p-Robo1 signaling on the pathogenesis of liver fibrosis, we established a model of S. japonicum-induced hepatic fibrogenesis in human MIR29A conditional knock-in mice." (PMID 37280619, 2023). "Former studies found that liver fibrosis was mediated by activating hepatic stellate cells through the Slit2/Robo1 and Slit2/Robo2 signal pathway." (PMID 35111704, 2021). "Previous studies identified that Robo1, as a potential target of miR-29a-3p, was a TGF-β1 target gene in mammary cells, which indicated that Robo1 may be involved in the progression of hepatic fibrosis." (PMID 37280619, 2023). "Our results revealed that miR-29a-3p-Robo1 signaling in HSCs mediated the pathogenesis of hepatic fibrosis, and overexpression of miR-29a-3p had a beneficial effect on schistosome-induced hepatic fibrosis by reducing the expression of Robo1 and preventing the activation of HSCs during infection." (PMID 37280619, 2023). "In addition, the mRNA levels of miR-29a-3p and Robo1 in the liver tissues of fibrosis patients were related to portal vein diameter and spleen thickness, which increased in parallel with the extent of hepatic fibrosis." (PMID 37280619, 2023). "Notably, our findings suggest that miR-29a-3p partially reverses schistosome-induced hepatic fibrosis by targeting Robo1 to prevent schistosomiasis-induced HSC activation during infection." (PMID 37280619, 2023). "In light of these findings, we hypothesized that miR-29a-3p and Robo1 were critically involved in schistosomiasis-induced hepatic fibrosis." (PMID 37280619, 2023). "We also observed that the blocking of Slit2/Robo1 signaling could attenuate phosphorylation of Smad2/3 in a TGF-β-independent way in liver fibrosis." (PMID 31242633, 2019). "However, our previous work presented that inhibition of Robo1 attenuated hepatic fibrosis through downregulation of the phosphorylation of both Smad2 and Smad3 in HSC independent of TGF-β1." (PMID 29743985, 2018).
liver fibrosis (continued). "These genes, including Robo1, Gabrb3, Gpc6, Ephb2 and Dlg2, are usually not expressed in healthy liver, and were reported to be upregulated in metabolic dysfunction-associated steatohepatitis and liver fibrosis." (PMID 39456836, 2024). "In particular, increased Robo1 and Ephb2 expression has been experimentally proven to promote MASH and liver fibrosis." (PMID 39456836, 2024). "Moreover, SLIT2 can act on ROBO1 and ROBO2 receptors and promote liver fibrosis by activating downstream PI3K/Akt signaling." (PMID 37238655, 2023).
autism (8 papers, 2011 to 2025). Persistent deficits in social interaction and communication and interaction as well as a markedly restricted repertoire of activity and interest as well as repetitive patterns of behavior. "Clinically, variants in ROBO1 have been reported in individuals with developmental disorder, language impairment, epilepsy, and autism." (PMID 40041274, 2023). "Robo1 and Robo2 has also been shown to be deficient in some cases of autism, suggesting that this pathway may be a possible mechanism by which HS deficiency could cause autism." (PMID 27089953, 2016). "Similar to the reduced expression of this gene in autism, expression levels for ROBO1 in AMD macular and peripheral retinas compared with normal maculas and peripheral retinas were significantly reduced." (PMID 21998696, 2011). "Our analysis supports the role of several genes/loci associated with autism (e.g., NRXN1, ADNP, 22q11 deletion) and identified new truncating (e.g., GRIK2, ROBO1, NINL, and IMMP2L) or recessive deleterious variants (e.g., KIRREL3 and CNTNAP2) affecting autism-associated genes." (PMID 30675382, 2019). "This also suggests a mechanism by which decreased Robo1 could lead to autism." (PMID 27089953, 2016).
bladder cancer (5 papers, 2022 to 2026). "Another circRNA, hsa_circ_0001495, increases Robo1 expression by targeting miR-527 to promote malignant behaviors of bladder cancer cells." (PMID 35210429, 2022). "Robo1 protein (ROBO1) is overexpressed in human bladder cancer tissues and paracarcinoma tissues." (PMID 39184050, 2024).
cervical cancer (5 papers, 2011 to 2024). A primary or metastatic malignant neoplasm involving the cervix. "Taken together, our findings demonstrated that RA inhibits proliferation, invasion and migration of cervical cancer cells via regulating miR-224-3p/Slit2/Robo1 signaling pathway, which indicates that RA can be an effective drug for CC therapies by targeting miR-224-3p and its downstream effectors." (PMID 33621954, 2021). "Hypermethylation at the promoters of genes (SLIT1, SLIT2, SLIT3, ROBO1, and ROBO3) involved in Slit-Robo pathway resulting in down-regulated gene expression was also indentified in invasive cervical cancer." (PMID 22140553, 2011). "Also, ROBO1 deletion is reported as one of the molecular alterations in small cell lung cancer, and SLIT-ROBO pathway genes are frequently altered and epigenetically regulated in breast, pancreas, and cervical cancers." (PMID 32552834, 2020).
glioblastoma (5 papers, 2013 to 2025). The most malignant astrocytic tumor (WHO grade IV). "Robo1 expression was mostly restricted to normal neurons, and overexpressed in astrocytic and glioblastoma cell lines." (PMID 39456164, 2024). "In order to find out by which mechanism the proteins Robo1 and Slit2 regulate radiation-induced motility of glioblastoma cells, we investigated the expression of the migration-associated proteins fascin and FAK/pFAKY925 and the EMT marker protein vimentin." (PMID 29864155, 2018). "75% of the grade-IV glioblastomas, 23.1% of grade-II, and 58.3% of grade-I glioblastomas tested positive for the expression of Robo1." (PMID 29864155, 2018). "Overexpression of Robo1 significantly decreased the motility of glioblastoma cells and inhibited the accelerated migration of wild-type cells after irradiation." (PMID 29864155, 2018). "Using time-resolved videography, it was possible to quantify the migration of the two glioblastoma cell lines U-373 MG and U-87 MG and to correlate it with the level of expression of Slit2/Robo1." (PMID 29864155, 2018). "Using qPCR, the mRNA expressions of Slit2 and Robo1 were quantified in two glioblastoma cell lines (U-373 MG and U-87 MG) with different malignancy characteristics regarding migration and radiation resistance, and the results were compared." (PMID 29864155, 2018). "In order to further test if Robo1 is indeed involved in regulating the motility of (irradiated) glioblastoma cells, we have diminished the expression of Robo1 through transfection of a specific siRNA." (PMID 29864155, 2018). "Radiation-induced changes in motility of glioblastoma cells on the one hand and Robo1- und Slit2-mediated motility changes on the other are potentially regulated by different mechanisms." (PMID 29864155, 2018). "Since expression differences are difficult to interpret in immunoperoxidase staining, we performed immunofluorescence imaging for ZEB1, ROBO1 and N-cadherin in glioblastoma specimens." (PMID 23818228, 2013). "Slit2 was found to act in different cells of glioblastoma tumors expressing Robo1 and Robo2." (PMID 39456164, 2024). "We therefore decided to investigate to what extent Slit2/Robo1 regulates the motility of glioblastoma cells and if this system could influence radiation-induced migration." (PMID 29864155, 2018). "qPCR and immunoblotting experiments in two different glioblastoma cell lines (U-373 MG and U-87 MG) with different malignancy revealed that both Slit2 and Robo1 are significantly lower expressed in the cell populations with the highest motility and that the expression was reduced after irradiation." (PMID 29864155, 2018). "In addition, the authors observed a reduction of Robo1 on the mRNA level in glioblastoma of all grades compared to the cortex." (PMID 29864155, 2018). "In addition, the immunohistochemical staining showed a higher expression of Robo1 in the neurons of the cortex than in glioblastoma tissue." (PMID 29864155, 2018). "New studies have shown that Slit2 and Robo1 could play important roles in leukocyte chemotaxis and glioblastoma cell migration." (PMID 29864155, 2018). "Our findings suggest that Robo1 expression might counteract migration and also radiation-induced migration of glioblastoma cells, a process that might be connected to mesenchymal-epithelial transition." (PMID 29864155, 2018). "Thus, the expression of Robo1 in glioblastoma remains uncertain and further studies are required." (PMID 29864155, 2018). "Therefore, we assessed the motility of Slit2 or Robo1 overexpressing glioblastoma cells." (PMID 29864155, 2018). "Therefore, we investigated whether the Slit2/Robo1 complex has an impact on the motility of glioblastoma cells and whether irradiation with therapeutic doses modulates this effect." (PMID 29864155, 2018). "ZEB1, N-cadherin, ROBO1, MGMT and Engrailed1 are frequently expressed in glioblastoma, confirming our experimental findings." (PMID 23818228, 2013).
glioblastoma (continued). "ZEB1 is preferentially expressed in invasive glioblastoma cells, where the ZEB1-miR-200 feedback loop interconnects these processes through the downstream effectors ROBO1, c-MYB and MGMT." (PMID 23818228, 2013). "Depending on the radiation dose, the motility of the analyzed Robo1-overexpressing glioblastoma cell lines remained unchanged or decreased compared to a non-irradiated control sample." (PMID 29864155, 2018). "Finally, the TCGA dataset supports the prognostic value of the ZEB1/miR-200/c-MYB pathway for glioblastoma, as well as significant co-occurrence of ZEB1, MGMT and ROBO1 in these tumours, and decreased levels of EGFR phosphorylation with reduced ZEB1 expression." (PMID 23818228, 2013).
leukemia (5 papers, 2015 to 2022). A malignant (clonal) hematologic disorder, involving hematopoietic stem cells and characterized by the presence of primitive or atypical myeloid or lymphoid cells in the bone marrow and the blood. "The results showed that ectopic expression of ROBO1 or ROBO2 produced varying degrees of an anti-tumour effect in leukaemia cells, whereas extracellular ROBO mutants lost this effect." (PMID 26608094, 2015). "Next, we investigated the effect of the addition of exogenous recombinant hSLIT2 together with the overexpression of ROBO1 or ROBO2 on the biological characteristics of leukaemia cells (magnification effect of SLIT2/ROBO signalling)." (PMID 26608094, 2015). "Overexpression of ROBO1 or ROBO2 produces anti-proliferative and pro-apoptotic effects in leukaemia cells in vitro." (PMID 26608094, 2015). "To further confirm the anti-tumour effect of ROBO1 and ROBO2 in MDS and leukaemia cells, we further performed experimetns in vitro by overexpressing of wild-type and mutant ROBO in leukaemia cells." (PMID 26608094, 2015). "In in vitro experiments, overexpression of ROBO1 or ROBO2 produces anti-proliferative and pro-apoptotic effects in leukaemia cells." (PMID 26608094, 2015). "Considering the low expression level of ROBO1 and ROBO2 in leukaemia cell lines, we transfected the ROBO1 and ROBO2 expression vectors into K562 and HEL cell lines using the SuperFect Transfection system to observe the effect of ROBO1 or ROBO2 on the biological characteristics of leukaemia cells." (PMID 26608094, 2015).
nasopharyngeal carcinoma (5 papers, 2012 to 2021). A carcinoma arising from the nasopharyngeal epithelium. "Overexpression of ROBO1 was significantly associated with worse overall and nodal relapse-free survival of nasopharyngeal carcinoma patients." (PMID 29523788, 2018). "In particular, the miRNA-218 and ROBO1 signaling axis has been studied extensively and correlates with metastasis and vascular patterning in pancreatic and nasopharyngeal cancers." (PMID 24705471, 2014). "For example, miR-218 can suppress nasopharyngeal cancer progression through down-regulation of BIRC5 (survivin) and the SLIT2 (slit guidance ligand 2)-ROBO1 (roundabout guidance receptor 1) pathway." (PMID 26553452, 2015).
osteosarcoma (5 papers, 2016 to 2025). A usually aggressive malignant bone-forming mesenchymal neoplasm, predominantly affecting adolescents and young adults. "Studies have also found that the SLIT2/ROBO1 axis promotes the Warburg effect of osteosarcoma by activating the SRC/ERK/c-MYC/PFKFB2 pathway." (PMID 36387908, 2022). "Transposon insertions were found in Srgap2, Enah, Slit2, Slit3, or Robo1 in 24 percent of primary tumors from mice with Sleeping Beauty derived osteosarcoma, further implicating the role of the Slit-Robo pathway in osteosarcoma." (PMID 27966608, 2016). "For instance, the Slit2/Robo1 axis has been linked to cancer proliferation via the Warburg effect in osteosarcoma, and it induces epithelial–mesenchymal transition (EMT) in colorectal epithelial cells by associating Src and E-cadherin with the Robo1 cytoplasmic domain." (PMID 41227302, 2025).
prostate carcinoma (5 papers, 2013 to 2018). A carcinoma that arises from epithelial cells of the prostate gland. "hsa-mir-1307 is predicted to target ROBO1, and promotes proliferation in prostate cancer by targeting FOXO3A." (PMID 30557297, 2018). "Five SNP-SNP interactions in three gene pairs (MMP16+ ROBO1, MMP16+ CSF1, and MMP16+ EGFR) were identified to be associated with aggressive prostate cancer in both groups." (PMID 23593148, 2013). "A reduced expression of Robo1 has been found in prostate cancer." (PMID 29864155, 2018). "Whereas ROBO1 could negatively regulate motility and invasiveness of primary prostate cancer cells and, thus, functions as a tumor suppressor to inhibit the progression of prostate cancer." (PMID 26610476, 2015). "The aim of our study was to address whether ROBO1 and ROBO2 expressions are altered in prostate cancers (PCA)." (PMID 24272677, 2014).
small cell lung carcinoma (5 papers, 2005 to 2024). Small cell lung cancer (SCLC) is a highly aggressive malignant neoplasm, accounting for 10-15% of lung cancer cases, characterized byrapid growth, and early metastasis. "Radioactive anti-Robo1 labeled with 90Y has been shown to exhibit antitumor activity against small cell lung carcinoma and HepG2 xenografts." (PMID 32256588, 2020). "In this study, we performed a biodistribution study and radioimmunotherapy (RIT) against ROBO1-positive small cell lung cancer (SCLC) models." (PMID 26017283, 2015). "In small cell lung cancer (SCLC), the Slit2/Robo1 signaling pathway inhibits the polarization of M2-like macrophages in the TME by suppressing the TGF-β1 signaling pathway." (PMID 39144141, 2024). "The human ortholog of robo, ROBO1 (also named DUTT1), was identified as a potential tumor-suppressor gene in a small-cell lung cancer cell line." (PMID 16254601, 2005).
developmental delay (4 papers, 2005 to 2016). "Consistent with an important developmental role of the ROBO1 locus, a 15-Mb deletion involving ROBO1 and a few neighboring genes was found in a child with developmental delay." (PMID 26877820, 2016). "We postulate that microdeletion within the ROBO1 gene at 3p12.3 may have played a role in the patient's developmental delay, since it has potential activity-dependent role in neurons." (PMID 25478007, 2014). "The human ROBO1/DUTT1 locus has been found deleted in a child with developmental delay and congenital anomalies but without cancers." (PMID 16254601, 2005).
diabetes (4 papers, 2011 to 2021). "In this study, we used streptozotocin (STZ)-induced diabetes in the rat to evaluate the expression of Slit2 and its receptor, Robo1, in background diabetic retinopathy." (PMID 28973045, 2017). "Our study examined the expression of Slit2 and its receptor, Robo1, in a rat model of streptozotocin-induced diabetes and in patients with proliferative diabetic retinopathy." (PMID 28973045, 2017). "The findings of this study indicate that STZ-induced diabetes in rats resulted in the time-dependent alteration of the expression of both Slit2 and Robo1 in retinal tissue." (PMID 28973045, 2017). "At 6 months after diabetes induction, both the Slit2 and the Robo1 expression patterns remained the same as at 3 months, with the exception that expression in the outer nuclear layer was decreased." (PMID 28973045, 2017). "Robo βKO mice, in which the genes Robo1 and Robo2 are deleted selectively in β cells, provide a unique model of altered islet spatial architecture without loss of β cell differentiation or islet damage from diabetes." (PMID 34231467, 2021).